HPSE (heparanase)
Diseases named in the same sentence as HPSE in open-access papers (continued):
Sharing a sentence is not in itself a finding about the gene and the disease.
glomerular diseases (11 papers, 2012 to 2025). "Heparanase‐mediated cleavage of cell surface HS has been reported to play a critical role in regulating inflammation, particularly during the progression of glomerular diseases." (PMID 40495439, 2025). "The over-expression of heparanase was observed in several glomerular diseases and glomerular heparanase up-regulation play a pivotal role in the development of DN." (PMID 28994624, 2017). "This study was designed to assess the heparanase activity in serum, urine, and granulocytes from patients with specific kinds of glomerulopathy." (PMID 27091112, 2017). "Nevertheless, additional research is required to elucidate the complex regulation of both eNOS and heparanase, and their interplay, in glomerular diseases." (PMID 27505185, 2016). "Taken together, our findings suggest that heparanase inhibition protects against podocyte injury and may represent a potential therapeutic strategy for glomerular diseases." (PMID 40495439, 2025). "Many glomerular diseases are characterized by reduced levels of HS in the GFB, and this reduced HS expression has been associated with increased glomerular expression of heparanase-1 (HPSE1) and albuminuria." (PMID 37180718, 2023). "Moreover, heparanase null mice and mice treated with heparanase inhibitor (PI-88) or neutralizing antibodies had mild kidney damage and proteinuria in experimental glomerular disease." (PMID 36293542, 2022). "The loss of GBM heparan sulfate may be the result of enzymatic cleavage by heparanase, which is often upregulated in glomerular disease, including in Heymann nephritis." (PMID 29988342, 2018). "The significance of heparanase produced by primed granulocytes in the course of particular glomerular diseases is still unknown." (PMID 27091112, 2017). "The regulation of heparanase expression by eNOS seems important for glomerular diseases, but may have important implications for other vascular beds outside the kidney as well." (PMID 27505185, 2016). "We provided clear evidence for the interplay between eNOS and heparanase in AN, which may be operative in other glomerular diseases as well, since in the majority of glomerular diseases heparanase expression is increased, whereas glomerular HS expression is decreased." (PMID 27505185, 2016). "Therefore, HPSE may serve as a therapeutic target for glomerular diseases." (PMID 35173145, 2022). "Being the sole mammalian endoglycosidase, HPSE not only exerts a unique enzymatic degradation of heparan sulfate (HS), thereby facilitating the development of albuminuria and further glomerular diseases, but also plays several non-enzymatic functions in kidney diseases." (PMID 35173145, 2022). "In conclusion, the question of “whether heparanase contributes to the pathogenesis of glomerular diseases” is still not fully answered." (PMID 36293542, 2022).
lung carcinoma (11 papers, 2014 to 2025). "Heparanase overexpression was associated with angiogenesis and lymphangiogenesis of lung cancer." (PMID 32121387, 2020). "Heparanase is highly expressed in all types of lung cancer, particularly LUAD, and its expression showed strong linkage with TNM staging in NSCLC and was negatively correlated with survival of patients with lung cancer." (PMID 41031217, 2025). "In order to reveal the significance of heparanase in lung cancer, we first employed lung carcinoma cell lines." (PMID 29721203, 2018). "Taken together, our results suggest that PG545 can be applied for lung cancer therapy in a personalized manner where conventional chemotherapy fails, thus bringing anti-heparanase treatment modalities closer to the clinic." (PMID 29721203, 2018). "Applying patient-derived lung cancer xenografts and a potent inhibitor of heparanase enzymatic activity (PG545) we investigated the significance of heparanase in the pathogenesis of lung cancer." (PMID 29721203, 2018). "In order to investigate the utility of anti-heparanase treatments in a lung cancer setting, we established a patient derived xenograft (PDX) model of lung cancer." (PMID 29721203, 2018). "We have previously shown that heparanase levels are substantially elevated in lung cancer, correlating with reduced patients survival." (PMID 29721203, 2018). "The significance of heparanase in lung cancer progression was further demonstrated by a profound tumor attenuation obtained in response to the heparanase inhibitor PG545." (PMID 29721203, 2018). "Five prognostic genes, including HPSE, DENND1C, GRWD1, HLA‐DQA1, and PDXK, were identified to further develop a risk signature, which exhibited moderate power for forecasting the prognosis of lung cancer patients in training, testing, and validation sets." (PMID 41031217, 2025). "Importantly, heparanase overexpression in HCC-827 lung carcinoma cells enhanced tumor growth by more than 2-fold compared to control (Vo) cells (p < 0.004)." (PMID 29721203, 2018). "The present study reveals the significance of heparanase in the pathogenesis of lung cancer." (PMID 29721203, 2018). "Applying established lung cancer cell lines, we first demonstrated that heparanase overexpression resulted in more aggressive tumor capacities both in vitro (cell invasion, anchorage-independent growth) and in vivo (xenograft formation, tumor growth and metastasis)." (PMID 29721203, 2018). "To bring anti-heparanase treatment modalities closer to the clinic, we established a lung cancer PDX model which better resembles the behavior and drug responsiveness of a given cancer patient, and more accurately reflects the clinical heterogeneity of the disease than cell lines." (PMID 29721203, 2018). "The overarching hypothesis guiding this research is that heparanase is a key regulator of the aggressive phenotype of NSCLC, and the objective of the study was to further elucidate the role of heparanase in lung cancer." (PMID 29721203, 2018). "Previous few studies identified that HPSE is a target of miR-1258 in breast and lung cancer." (PMID 27270326, 2016). "Hence, elevated heparanase procoagulant activity in patients with lung cancer reveals a new mechanism of coagulation system activation in malignancy." (PMID 25386347, 2014). "In A549 cells, heparanase exhibited opposite actions with IGFBP3, a potential protective factor in lung cancer." (PMID 41031217, 2025). "Consistently, expression of HPSE was enhanced in tumor samples in both TCGA and GSE18842 cohorts as well as in the platelet of advanced lung cancer patients." (PMID 41031217, 2025). "We next examined the capacity of heparanase inhibitor, PG545, to restrain the tumorigenic capacity of lung carcinoma cells (LLC)." (PMID 29721203, 2018). "Previous studies have shown that heparanase upregulation is observed in the majority (90%) of lung carcinoma biopsy specimens, but not in normal lung tissue collected distant from the tumor lesions." (PMID 29721203, 2018).
lung carcinoma (continued). "To this end, we applied overexpression and heparanase inhibition (PG545, a synthetic fully sulfated tetra saccharide functionalized with a cholestanyl aglycon) strategies and examined pro-tumorigenic properties of lung cancer cells in vitro and tumor growth in vivo." (PMID 29721203, 2018).
ovarian carcinoma (11 papers, 2007 to 2026). A malignant neoplasm originating from the surface ovarian epithelium. "In an ovarian cancer model, HIF-1α suppressed miR-299 in the hypoxic cancer cells that were associated with the increased expression of heparanase HPSE1 and an elevated radioresistance." (PMID 33806538, 2021). "Zhang and colleagues identified heparanase as good marker for ovarian cancer metastasis with sensitivity of 69.6% and specificity of 67.2%." (PMID 26488476, 2015). "This experiment was conducted using ovarian carcinoma cell line, OC MZ-6; a cell line previously shown to contain heparanase in immunofluorescence experiments." (PMID 22719856, 2012). "Interestingly, elevated heparanase levels have been found in ovarian cancer (OC), which has a notably high incidence of venous thrombosis." (PMID 42084761, 2026). "Ovarian cancer cell proliferation and migration is effectively suppressed by PG545, a completely sulfated synthetic tetrasaccharide with anti-heparanase activity, when treatment is combined with paclitaxel and cisplatin." (PMID 35118073, 2021). "These experiments demonstrate that heparanase was strongly expressed by ovarian cancer cells, but was virtually absent from endothelial cells and normal ovarian tissues." (PMID 17437011, 2007). "Furthermore, high HPSE mRNA expression was found in primary gastric SRCA cells, KATO-III cell line as well as in an ovarian cancer cell line (OVCAR-3) as compared to gastric non-SRCA (AGS) cell lines." (PMID 30333909, 2018).
acute pancreatitis (10 papers, 2017 to 2024). An acute inflammatory process that leads to necrosis of the pancreatic parenchyma. "A similar observation was noted for IL-6 and STAT3 phosphorylation which indicates the association of heparanase with the activation of key signaling pathways related to acute pancreatitis." (PMID 34681753, 2021). "However, the function and underlying mechanism of heparanase in acute pancreatitis remain poorly understood." (PMID 34016163, 2021). "Parabacteroides, a commensal bacterium identified in the gut microbiota, plays a crucial role in mitigating acute pancreatitis, particularly in the context of heparanase-induced exacerbation." (PMID 38410384, 2024). "The administration of Parabacteroides has been shown to alleviate acute pancreatitis by producing acetate and reducing neutrophil infiltration in both wild-type and heparanase-transgenic mice." (PMID 38410384, 2024). "Parabacteroides generate acetate to mitigate heparanase-exacerbated acute pancreatitis by reducing neutrophil infiltration." (PMID 36860489, 2023). "Administration of Parabacteroides alleviated heparanase-exacerbated acute pancreatitis through reducing neutrophil infiltration." (PMID 35847065, 2022). "Acute pancreatitis was induced in wild-type and heparanase-transgenic mice by administration of caerulein." (PMID 34016163, 2021). "Administration of Parabacteroides alleviated acute pancreatitis in wild-type and heparanase-transgenic mice." (PMID 34016163, 2021). "In a mouse model of acute pancreatitis, heparanase overexpression resulted in elevated levels of IκB phosphorylation and correlated with increased TNF-α expression." (PMID 34681753, 2021). "Here, we investigated the interplay between heparanase and the gut microbiota in the development of acute pancreatitis." (PMID 34016163, 2021). "In addition, Parabacteroides produced acetate to alleviate heparanase-exacerbated acute pancreatitis through reducing neutrophil infiltration." (PMID 34016163, 2021). "Interestingly, in a model of acute pancreatitis, cathepsin L has also been shown to be regulated by heparanase, representing a self-sustaining loop which generates continuous heparanase activity." (PMID 34681753, 2021). "Heparanase exacerbated acute pancreatitis in a gut microbiota-dependent manner." (PMID 34016163, 2021). "As compared with wild-type mice, acute pancreatitis was exacerbated in heparanase-transgenic mice." (PMID 34016163, 2021). "Interestingly, in acute pancreatitis in mice and colitis in mice and humans, heparanase expression is strongly induced or elevated in pancreatic acinar cells and gut epithelial cells, respectively, and contributes to local inflammation." (PMID 29415062, 2018).
glomerulonephritis (10 papers, 2016 to 2025). A renal disorder characterized by damage in the glomeruli. "In HPSE-deficient mice, however, renal function was improved and proteinuria was reduced compared to wildtype mice upon inducing experimental glomerulonephritis." (PMID 33951113, 2021). "In this study, we confirmed that cortical HPSE mRNA expression was increased in the LPS-induced glomerulonephritis mice compared to controls but remained largely unaltered with the treatments." (PMID 37475889, 2023). "The endoglycosidase heparanase cleaves HS and hence appears to be involved in the pathogenesis of kidney injury and glomerulonephritis." (PMID 36293542, 2022). "The induction of experimental glomerulonephritis resulted in increased HPSE expression, a decreased glomerular HS expression and increased proteinuria in wildtype mice." (PMID 33951113, 2021). "The aim of this study was to assess the significance of heparanase in the pathogenesis of particular glomerulonephritis types." (PMID 27091112, 2017). "We previously showed that heparanase, a heparan sulfate (HS) specific endoglycosidase, is essential for the development of proteinuria and renal damage in experimental DN and glomerulonephritis." (PMID 27505185, 2016).
prostate carcinoma (10 papers, 2010 to 2024). A carcinoma that arises from epithelial cells of the prostate gland. "Malignant transformation in prostate cancer has been shown to be associated with considerable increase in the expression of heparanase at both mRNA and protein levels." (PMID 33490732, 2021). "Collectively, these results proved an additional mechanism by means of which HPSE can contribute to prostate cancer progression and metastasis, and further studies will be necessary to clarify its potential as a pharmacological goal." (PMID 35965510, 2022). "Since prostate cancer also has an increased expression of HPSE, we decided to verify whether this increase could be able to regulate EMT and cancer stem cells properties of prostate cancer." (PMID 35965510, 2022). "Heparanase (HPSE), the sole mammalian endoglycosidase capable of degrading heparan sulfate (HS), is also involved in prostate cancer progression." (PMID 35965510, 2022). "Lerner et al111 reported a highly statistically significant (P < .0001) prevalence of heparanase overexpression in prostate carcinomas versus noncancerous tissue, as well as a strong correlation between tumor grade and the extent of heparanase expression." (PMID 33490732, 2021).
Hyperglycemia (9 papers, 2005 to 2023). An increased concentration of glucose in the blood. "We conclude that upregulation of heparanase in fat tissue was associated with endothelial injury and inflammation in hyperglycemia conditions." (PMID 31890010, 2019). "Heparanase upregulation in fat tissue was associated with endothelial injury and inflammation in hyperglycemia conditions." (PMID 31890010, 2019). "This study demonstrates that both high glucose and heparinase I cause EC injury and suggests a link between hyperglycemia and heparanase induction in diabetic complications." (PMID 16086844, 2005). "Therefore, as hyperglycemia is prolonged, heparanase is likely to cause increasingly severe pancreatic β-cell injuries." (PMID 36292936, 2022). "Hyperinsulinaemia and hyperglycaemia driven breakdown of HS via increased heparanase enzymatic cleavage and increased sulphate wastage, results in decreasing osteocyte perlecan, further contributing to harming osteocyte viability and function." (PMID 34572351, 2021). "We have demonstrated that hyperglycemia-induced up-regulated expression of active heparanase (50 kDa) in ECs was inhibited by apoEdp treatment in vitro." (PMID 23284911, 2012). "Heparanase production, induced by hyperglycemia, and subsequent degradation of heparan sulfate may contribute to endothelial injury." (PMID 16086844, 2005). "Therefore, we developed diabetic mice/cell models, applied biological experiments to study the alterations of Sdc1 and HPSE in high-glucose/hyperglycaemia (HG) conditions, and then investigated the subsequent changes of barrier function of intestinal epithelium and the possible regulation mechanism." (PMID 25702768, 2015). "HSPG degradation by heparanase upregulation may contribute to EC injury by hyperglycemia." (PMID 16086844, 2005). "Hyperglycemia in T2DM induces significant alteration of HSPG in the endothelium and brain by increasing expression of heparanase enzyme which degrades HSPG." (PMID 37173803, 2023). "Hyperglycaemia oxidative damage, resulting in AGE, and receptor for AGE (RAGE) production, increases heparanase expression." (PMID 34572351, 2021). "Syndecan-1 (Sdc1) and its endo-beta-d-glucuronidase heparanase (HPSE) are implicated in maintenance of intestinal epithelial barrier (IEB), but their alterations and roles in high-glucose/hyperglycaemia (HG) conditions have not been fully investigated." (PMID 25702768, 2015). "Hyperglycemia is known to induce the expression of the ECM-degrading enzyme, heparanase." (PMID 23284911, 2012). "Hyperglycemia following pancreatic β-cell injury through STZ treatment suppresses the expression of the transcription factor PPARγ, resulting in the cancellation of the inhibition of heparanase expression by PPARγ and the promotion of HS degradation on pancreatic islets by heparanase." (PMID 36292936, 2022).
chronic kidney disease (8 papers, 2012 to 2024). Impairment of the renal function secondary to chronic kidney damage persisting for three or more months. "Overall, the present findings prove that heparanase, independently of the underlying nephropathy, regulates the development of fibrosis in chronic kidney disease modulating EMT and inflammation." (PMID 33804258, 2021). "Urinary heparanase was markedly elevated in kidney-transplanted patients and urinary heparanase was markedly elevated and associated with proteinuria in chronic kidney disease (CKD) patients." (PMID 28994624, 2017). "Here, we quantified blood and urine heparanase levels in renal transplant recipients and patients with chronic kidney disease (CKD), and assessed whether alterations in heparanase levels correlate with proteinuria and renal function." (PMID 23028487, 2012). "There is also evidence indicating that in chronic kidney disease, granulocytes are primed, but all available data about this fact involved patients with advanced chronic kidney disease and heparanase was not checked in these evaluations." (PMID 27091112, 2017). "Likewise, increased heparanase activity was detected in urine samples from diabetic patients with microalbuminuria, nondiabetic nephrotic syndrome, chronic kidney diseases (CKD) and kidney transplanted patients." (PMID 28388547, 2017).
colitis (8 papers, 2014 to 2023). Inflammation of the colon. "Heparanase was shown to stimulate macrophage activation, which in colitis induces production (i.e., via TNFα) and activation (via cathepsin L) of latent heparanase in the colon epithelium, together generating a vicious cycle that powers colitis and the associated tumorigenesis." (PMID 24465803, 2014). "Another study to show TNF-α induction of heparanase (during colitis-associated tumorigenesis) proposed that since TNF-α also induced upregulation of EGR1 that TNF-α induced heparanase expression via activation of EGR1, although this is yet to be confirmed." (PMID 34681753, 2021).